ZNF22 (zinc finger protein 22)
Description:
Binds DNA through the consensus sequence 5'-CAATG-3'. May be involved in transcriptional regulation and may play a role in tooth formation (By similarity).
Synonyms: KOX15; HKR-T1; ZNF422; Zfp422
Tractability: PROTAC: ubiquitination databases record sites on it; its protein half-life has been measured.
Gene: Protein-coding gene on chromosome 10 (45,000,293 to 45,005,329, forward strand). Ensembl gene ENSG00000165512.
Subcellular location: Nucleus
Subcellular location (Human Protein Atlas): Nucleoplasm
Gene Ontology:
Molecular function: protein binding; DNA binding; DNA-binding transcription factor activity; zinc ion binding
Biological process: odontogenesis; regulation of DNA-templated transcription; regulation of gene expression
Cellular component: nucleoplasm; nucleus
Genetic constraint (gnomAD): Loss-of-function variants: 15 observed, 18.99 expected, observed/expected ratio (o/e) 0.79, 90% interval 0.53 to 1.22. The upper end of that interval is the gene's LOEUF score, 1.22, which puts it in group 5 of 6, group 1 being the genes least tolerant of losing a copy. Missense variants: 272 observed, 290.49 expected, observed/expected ratio (o/e) 0.94, 90% interval 0.85 to 1.03. Synonymous variants: 84 observed, 96.63 expected, observed/expected ratio (o/e) 0.87, 90% interval 0.73 to 1.04.
Homologues: Orthologues: chimpanzee ZNF22 (100% identical), macaque ZNF22 (99% identical), rabbit ZNF22 (95% identical), pig ZNF22 (92% identical), dog ZNF22 (92% identical), mouse Zfp422 (86% identical), rat Zfp422 (86% identical), zebrafish si:ch1073-224n8.1 (33% identical), zebrafish znf16l (32% identical), zebrafish si:dkey-210j14.3 (24% identical), zebrafish si:dkey-210j14.4 (22% identical), zebrafish si:ch211-284e13.5 (20% identical). Paralogues in human: ZFP41 (30% identical), ZNF257 (20% identical), ZNF98 (20% identical), ZNF680 (19% identical), ZNF737 (19% identical), ZNF430 (18% identical), ZNF626 (18% identical), ZNF730 (18% identical), ZNF92 (18% identical), ZNF723 (18% identical), ZNF253 (17% identical), ZNF273 (17% identical), and 6 more.
Diseases named in the same sentence as ZNF22 in open-access papers:
ZNF22 is named in the same sentence as 4 diseases in open-access papers, as found by Europe PMC text mining. Sharing a sentence is not in itself a finding about the gene and the disease. The quoted sentences say what the papers report.
glioma (1 paper, 2022). A benign or malignant brain and spinal cord tumor that arises from glial cells (astrocytes, oligodendrocytes, ependymal cells). "We would like to offer a unique strategy for CNS infection and glioma therapy based on our study of the association between ZNF22, HDAC3, TJ-associated proteins, and BBB/BTB permeability." (PMID 36518188, 2022). "ZNF22 was reported to be associated with the prognosis of glioma." (PMID 36518188, 2022). "This may provide a new direction for future research into the role of ZNF22 in glioma." (PMID 36518188, 2022). "The expression of ZNF22 and HDAC3 in glioma-exposed endothelial cells (GECs) of BTB were detected transcription real-time PCR or western blot." (PMID 36518188, 2022). "GO analysis of ZNF22 and HDAC family in glioma using bioinformatics revealed that ZNF22 and HDAC3 were involved in regulating transcription GO: 0006357 (P < 0.05)." (PMID 36518188, 2022). "We revealed ZNF22 (P < 0.05) and HDAC3 (P < 0.05) to be highly expressed in gliomas in a difference analysis." (PMID 36518188, 2022). "In previous studies, ZNF22 was thought to be involved in the development of teeth, and its mechanism of action in gliomas or others was still not thoroughly elucidated." (PMID 36518188, 2022).
cancer (3 papers, 2020 to 2023). A tumor composed of atypical neoplastic, often pleomorphic cells that invade other tissues. "However, LOC91450 and ZNF22 have not been reported in cancer." (PMID 32849822, 2020).
tumor (3 papers, 2016 to 2023). "The primary goals of this study were to investigate the potential roles of ZNF22 and HDAC3 as a histone deacetylase in regulating an increases in blood-tumor barrier (BTB) permeability and some of the possible molecular mechanisms associated with this effect." (PMID 36518188, 2022).
ZNF22 also shares sentences with these, for which no sentence is quoted: allergies (1 paper).